CX3CL1 (C-X3-C motif chemokine ligand 1)
Diseases named in the same sentence as CX3CL1 in open-access papers (continued):
Sharing a sentence is not in itself a finding about the gene and the disease.
tumor (continued). "It is important to evaluate in future research whether differential fragments of CX3CL1 are generated in the tumor microenvironment due to changes in expression patterns of metalloproteases in tissues undergoing remodeling." (PMID 33391453, 2021). "Indeed, these studies suggest that the major monocyte recruiting pathways (M-CSF/CSF-1R, CCL2/CCR2, CCL3/CCR1, CCL3/CCR5, CCL5/CCR5 and CX3CL1/CX3CR1) enable tumor survival by supplying the TME with pro-tumorigenic TAMs." (PMID 34988021, 2021). "Interestingly, a previous study observed that CX3CR1 ectopic expression improved the recruitment of adoptively transferred T cells toward CX3CL1-generated cancers, leading to the augmentation of T-cell infiltration and reduction of tumor growth." (PMID 35140706, 2021). "Furthermore, ICAM-1 was induced by vertebral endothelial cells and then activated through CX3CL1, which facilitates the adhesion of circulating tumor cells and showed close interaction between these molecules." (PMID 34063821, 2021). "CX3CL1 is a multifunctional chemokine that is involved in numerous biological processes, such as immune cell attraction and enhanced tumor immune cell interaction, but also in enhancing tumor cell proliferation and metastasis." (PMID 34070094, 2021). "CX3CL1 regulates the vertebral micro-vascular barrier and induces disruption of vertebral marrow endothelial cells, thus promoting the extravasation of cancer cells with subsequent tumor growth specific to the spine." (PMID 34063821, 2021). "In a C57BL/6 mice carcinogenesis model, where mice were inoculated with either Lewis lung carcinoma cells (3LL) or 3LL cells overexpressing CX3CL1 (3LL-FK), the authors found a decrease on tumor size in mice inoculated with 3LL-FK compared to those inoculated with 3LL WT cells." (PMID 33391453, 2021). "However, in HTM, we did not detect CX3CL1-induced chemotactic function, which would be reflected by an increased immune cell tumor infiltration in CX3CL1 overexpressing MDA-MB-453 tumors, but we observed enlarged spleens in these mice." (PMID 34070094, 2021). "Sustained tumor growth requires angiogenesis, and indirect evidence indicates that CX3CL1 could play a pro-angiogenic role in cancer." (PMID 33391453, 2021). "CX3CL1 also participate in the process of tumor immune cells infiltration and invasion." (PMID 34460437, 2021). "Additionally, in the tumor niche it is possible that CX3CL1 increases the production of platelet-derived factor 4 (PF-4)/CXCL4 in macrophages." (PMID 32466280, 2020). "Our previous studies found that CX3CL1 quickly activated Src signaling in several tumor cells." (PMID 32390803, 2020). "CX3CL1 reduces primary tumor growth and spontaneous liver metastases." (PMID 32799418, 2020). "However, CX3CL1 involvement in the TEM of tumor cells by regulating vertebral micro-vascular endothelial barrier function has not yet been reported in the literature." (PMID 32390803, 2020). "In addition, it is postulated to simultaneously increase the expression of CX3CL1 and other cytokines that enhance the immune response, e.g., IL-2, which significantly increases the effect of CX3CL1 in a tumor." (PMID 32466280, 2020). "Thus, their corresponding ligands such as CCL5, CXCL9, CXCL10, and CX3CL1 effectively guide CD8+ CTL mobilization from regional lymph nodes to tumor tissues." (PMID 31991604, 2020). "The CXCR4 ligand CXCL12 and the CX3CR1 ligand CX3CL1 were downregulated in the tumour tissue." (PMID 32439888, 2020). "Therefore, a study in PDAC patients showed evidence that high expression of the CX3CL1/CX3CR1 axis in tumor tissues led to a poor prognosis for OS." (PMID 31991604, 2020). "Furthermore, CX3CL1, which is rich in vertebral microenvironments, chemo-attracts many tumor cells from blood circulation to the spine." (PMID 32390803, 2020).
tumor (continued). "CCR5 and CX3CL1 were demonstrated to promote the expression of antiapoptotic and tumor-promoting proteins such as Bcl-xl, Bcl-2, and C-IAP1, as well as to reduce the expression of apoptotic proteins including cleaved caspase-3 and -9, PARP, and Bax via the NF-κB pathway." (PMID 31991604, 2020). "Therefore, gene therapy with the use of the adenoviral vector, plasmid vector or DNA vaccine with the CX3CL1 gene that increases the expression of CX3CL1 in the tumor has a therapeutic effect." (PMID 32466280, 2020). "CX3CL1-dependent immune processes can be offset by some mechanisms present in the tumor." (PMID 32466280, 2020). "Importantly, the inhibition of Src/p115 RhoGEF/ROCK signaling in VMECs not only blocked CX3CL1-induced VMEC monolayer hyper-permeability but also inhibited tumor cell TEM." (PMID 32390803, 2020). "In the present study, we determined whether CX3CL1 was involved in vertebral micro-vascular barrier disruption and promoted tumor cell TEM after circulating tumor cells were arrested in the vertebral micro-vasculature." (PMID 32390803, 2020). "We identified a novel signaling pathway in which miR-561-5p alters the tumor microenvironment by suppressing its target CX3CL1 and consequently blocking the recruitment and infiltration of NK cells, thereby allowing HCC cells to evade NK cell cytotoxicity, proliferate, and metastasize to the lungs." (PMID 31367257, 2019). "Preclinical studies confirm the tumor-suppressive effect of CX3CL1 in several cancer models." (PMID 31482487, 2019). "However, as described for the CXCR3 system, the CX3CR1 receptor is also able to facilitate tumor cell migration and, thereby, metastasis in CX3CL1-rich tissues, e.g. the bone or the brain." (PMID 31482487, 2019). "The pathophysiological role of the CX3CL1/CX3CR1 axis in the interaction between tumor cells and the microenvironment has been demonstrated in several solid tumors, such as breast and prostate and in different types of B cell lymphomas and chronic lymphocytic leukemia." (PMID 30845779, 2019). "Moreover, expression of the transmembrane form of CX3CL1 in neurons, endothelial cells or peritoneal cells promotes tumor cell adhesion and site-specific metastasis of CX3CR1-expression prostate, ovarian, or pancreatic tumor cells." (PMID 31482487, 2019). "However, in vivo, CX3CL1 reduced tumorigenesis and pulmonary metastasis, with CX3CL1 suppression promoting tumor development." (PMID 31367257, 2019). "Conversely, in anti-tumour immunity, the high expression of IFNγ in the tumour milieu dictates high-endothelial expression of CX3CL1 that overrides the action of chemokines required for HPMo transmigration, thus imposing a state of continuous crawling for proangiogenic monocytes in the vessel lumen." (PMID 29367702, 2018). "Conversely, Gata3 binding to Cx3cl1 was higher in endothelial cells from DLD1 tumours." (PMID 29367702, 2018). "Thus, we identified the cytokine CX3CL1 as a direct NF-κB (RelA) target gene, which attracts immune cells to the site of tumor and thereby modulating the resistance of the cancer cells through a paracrine signaling pathway." (PMID 29867042, 2018). "Together, these data suggest that a miRNA network combinationally targeting the core regulons (e.g., CSF1, CX3CL1) may be guaranteed by miR-125b in NCCIT tumor cells." (PMID 30237497, 2018). "Our results suggested that expression of VEGF-A by tumour cells along with the inflammatory cytokine TNF might program tumour vasculature to maintain expression of CX3CL1 at low levels enabling extravasation of HPMo." (PMID 29367702, 2018). "The up-regulation of CX3CL1 in the tumor microenvironment might attract infiltrating IFN-γ-expressing NK cells that, in turn, stimulate the expression of FasL to activate apoptosis in tumor cells." (PMID 28399860, 2017). "Therefore, JC-001 appears to inhibit tumor progression by modulating the CX3CL1/IFN-γ/FasL signaling pathway." (PMID 28399860, 2017).
tumor (continued). "Notably, blockade of the CX3CL1/CX3CR1 axis suppresses tumour growth, whereas inactivation of CDKs elicits the opposite effect." (PMID 29234059, 2017). "We speculate that high CX3CL1 expression might recruit Mo-MDSCs to tumour, thereby increasing PD-L1-independent immunosuppression." (PMID 29234059, 2017). "Tumor tissues set up different strategies to escape immune recognition and in particular to affect chemokine/chemokine receptor axes such as CX3CL1/CX3CR1, which are crucial for the recruitment of cells such as CD56dim NK cells exerting tumor suppressive properties." (PMID 28791023, 2017). "Thus, deletion of p16Ink4 and p21Cip1/Waf1 reduces CX3CR1 expression, thereby inhibiting Mo-MDSC accumulation in tumours expressing CX3CL1 and suppressing the tumour progression in mice." (PMID 29234059, 2017). "Furthermore, slower growth of LLC tumour allografts in p16/p21-DKO mice was observed when CX3CL1 was ectopically expressed in LLC cells." (PMID 29234059, 2017). "Ectopic expression of chemokines/chemoattractants known to preferentially attract effector lymphocytes, including CXCR3 ligands as well as CX3CL1 and chemerin, was shown to positively affect the antitumor nature of tumor-infiltrating lymphocytes with a large proportion of NK cells." (PMID 27766097, 2016). "The dual function of CX3CL1 as chemoattractant for leukocytes and adhesion molecule for tumor cells that express the receptor may explain the discrepancies reported in the literature regarding the tumorigenesis process." (PMID 24799766, 2014). "In conclusion, the CX3CR1/CX3CL1 axis could represent a potential therapeutic approach using antagonists to CX3CR1 capable to inhibit tumor neurotropism in PADC." (PMID 24799766, 2014). "Thus, CXCL9, CXCL10, CXCL16, CCL5, and CX3CL1 can be used to efficiently mobilize CTLs from regional lymph nodes to tumor tissues with an objective to enhance CTL-mediated tumor destruction." (PMID 24966464, 2014). "Results demonstrated that CX3CL1 gene expression is induced in normal breast epithelium of ER− tumors compared to normal breast epithelium of ER+ tumors, suggesting that CX3CL1 expression may be an early marker of ER− tumor formation." (PMID 23029290, 2012). "As a result, the NFκB pathway may provide a targetable approach for inhibition of iFGFR1-mediated CX3CL1 gene and protein expression in order to reduce macrophage migration and potential tumor growth and progression." (PMID 23029290, 2012). "As a result of both the adhesion and chemoattractant activities of the chemokine, the CX3CL1/CX3CR1 complex may mediate either pro- or anti-tumor effects." (PMID 21750716, 2011). "Finally, we investigated the impact of GILZ and CX3CL1 on tumor growth in vivo by using a mouse subcutaneous xenograft model." (PMID 21750716, 2011). "CX3CL1 may participate to this action in EOC through autocrine effects that should contribute to its pro-tumor potential." (PMID 21750716, 2011). "Here, we asked whether this chemokine has an impact on tumor cell proliferation, as suggested by the correlation of CX3CL1 and Ki-67 immunostainings in EOC specimens." (PMID 21750716, 2011). "The cytokine IL1β, identified by the IPA analysis as linkedto the activation of the pro-metastatic chemokines CX3CL1 andCCL20, was up-regulated in the tumour cellpopulations PIN and H-PCA, whereas the expression ofIL1R1, which mediated the activity ofIL1β, follows an opposite trend." (PMID 21479216, 2011). "Drug treatment may also have an impact on the effect of CX3CL1 in neoplasms." (PMID 41210693, 2025). "However, emerging evidence from several studies paradoxically suggests that CX3CL1 may exhibit tumor-suppressive effects in OSCC, contradicting its established pro-tumorigenic role." (PMID 41445742, 2025). "Moreover, the positive relationship between PYGB and CX3CL1, a chemokine involved in recruiting immune cells to the tumor site, indicated that PYGB might influence the infiltration of immune cells into the tumor microenvironment." (PMID 40458414, 2025).
tumor (continued). "Together with the decreases in Tim-3 and CX3CR1 levels in pNK cells after interaction with MCF-7 spheroids, these findings may indicate the involvement of the Tim-3/galectin-9 and CX3CR1/CX3CL1 pathways in the regulation of the cytotoxic response of pNK cells to MCF-7 tumor cells in the 3D model." (PMID 39457710, 2024). "However, in the breast cancer tumor microenvironment, CX3CL1 overexpression attracts NK cells, which then inhibits tumor growth and metastasis, and thus improves the efficacy of trastuzumab in the treatment of low-expressing human epidermal growth factor receptor 2 cancers." (PMID 39309440, 2024). "Moreover, IL-15 and CX3CL1 plasma levels were positively correlated with markers of inflammation and high tumor burden (fibrinogen, lactate dehydrogenase, C-reactive protein, cell-free DNA, CXCL9) at pre-lymphodepletion, a biochemical makeup that has been associated with ICANS." (PMID 38833312, 2024). "In addition, the ROC curves demonstrated that CX3CL1 expression could differentiate between normal and tumor tissues." (PMID 37153002, 2023). "We hypothesized our mAb could inhibit migration of CX3CR1+ tumor cells towards a CX3CL1 gradient." (PMID 37771579, 2023). "CX3CL1 expression was found to be positively connected with CD4+ T cells infiltration across most TCGA cancer types, as well as activated mast cells and M1 macrophage cells across several particular tumor types, indicating that CX3CL1 may also reflect the immune status in various cancers." (PMID 37153002, 2023). "In addition, the low expression of CX3CL1 in cluster 1 may increase tumor invasiveness and promote tumor growth." (PMID 36159780, 2022). "Therefore, we speculate that besides promoting the invasion directly by affecting on tumour cells, in vivo injection of CX3CL1 may also be involved in the recruitment of M2 macrophages with high expression of CX3CR1." (PMID 33191645, 2021). "Moreover, the CX3CL1 transfection increased tumor formation in a dose-dependent manner." (PMID 34070094, 2021). "Therefore, CX3CL1/CX3CR1-mediated signaling may be a new potential target for therapies that inhibit TAM recruitment into the tumor microenvironment." (PMID 34178692, 2021). "However, the mechanisms by which CX3CL1 in vertebrae mediates tumor cell spine metastasis remain unclear." (PMID 32390803, 2020). "However, the role of CX3CL1 in tumor cell trans-endothelial migration (TEM) in the spine remains unknown." (PMID 32390803, 2020). "However, whether CX3CL1 further breaks the vertebral micro-vascular barrier and promotes tumor cell TEM remains unknown." (PMID 32390803, 2020). "However, there are also studies in support of tumor-promoting effects of the CX3CL1-system: one study attributed a pro-metastatic function to the CX3CR1 receptor; however, the authors did not use an immuno-competent mouse model and, thereby, excluded the influence of immune modulatory effects." (PMID 31482487, 2019). "The combined method could improve the CX3CL1 expression and further attract NK cells into tumor." (PMID 31057396, 2019). "Furthermore, the high conservation between human and mouse CX3CR1 and the known cross-reactivity of mouse chemokine Cx3cl1 with the human receptor might account for the reduced extravasation of HPMo to tumours induced by the impairment of VEGF-A signalling." (PMID 29367702, 2018). "Such an approach may be optimally tailored by choosing a chemokine ligand and receptor matching pair that overlaps with physiological chemokine ligand expression in specific tumours e.g. using CX3CL1/CX3CR1 matching in ovarian cancer or CCL-19/CCR7 matching in breast cancer." (PMID 29157300, 2017). "However, the present results suggest that CDK inhibition may accelerate tumour growth by enhancing Mo-MDSC infiltration into tumours expressing CX3CL1 in vivo." (PMID 29234059, 2017). "Thus, secreted CX3CL1 might act as a chemokine that induces infiltrating immune cells to attack tumor cells." (PMID 28399860, 2017).
tumor (continued). "We next investigated whether endogenous CX3CL1 stimulates tumor cell proliferation." (PMID 21750716, 2011). "Mechanistically, dendritic cell clocks control expression of Cx3cl1, driving recruitment of CX3CR1+CD8+ T cells and thereby reshaping the tumor immune microenvironment to enhance immunotherapy efficacy." (PMID 41279119, 2025). "The increases macrophage secretion of CX3CL1, recruiting CD4+ T cells and NK cells to tumor sites and enhancing anti-tumor responses." (PMID 41417432, 2025). "On the other hand, the CX3CL1/CX3CR1 axis promotes cancer cell proliferation, migration, and invasion, recruits pro-tumor immune cells, and promotes tumor angiogenesis through TAMs." (PMID 41445742, 2025). "CX3CR1 is the sole receptor for CX3CL1, and the CX3CL1/CX3CR1 axis has been shown to regulate functions such as inflammatory cell chemotaxis and tumor cell adhesion." (PMID 40145607, 2025). "For example, recent studies have shown that inhibiting the CX3CL1‒CX3CR1 axis, particularly with drugs such as the Src inhibitor saracatinib, can block the chemotactic effect of CX3CL1 and reduce tumor metastasis in other cancers." (PMID 40051011, 2025). "GAM interact bidirectionally with neoplastic cells through colony-stimulating factor-1 and C-X3-C motif chemokine ligand-1 (CX3CL1), fostering a feed-forward loop that entrenches the M2-like phenotype and supports tumour proliferation." (PMID 40995359, 2025). "This relationship highlights the role of CX3CL1 as a key factor that recruits immunosuppressive cells to the tumor site through a CX3CR1-dependent mechanism, thus modulating the tumor microenvironment." (PMID 40051011, 2025). "Herein, several KLF4-assocaited genes, C10orf54 and CD274 were correlated with tumor suppression, while others, including CX3CL1, TNFRSF4, and IL1A, were correlated with tumor stimulation." (PMID 40299916, 2025). "Conversely, loss of YTHDF2 in tumor cells led to macrophage recruitment via CX3CL1 and enhanced mitochondrial respiration in CD8 + T cells by impairing tumor glycolysis." (PMID 39987091, 2025). "Overexpression of CX3CL1 inhibits OSCC cell proliferation, invasion, migration, and stemness, and can partially reverse the tumor-promoting effect of lipopolysaccharide (LPS)." (PMID 41445742, 2025). "Downregulation of TRADD, CX3CL1, and ILI24 implies dysregulation in TNFR1 signaling, immune recruitment, and tumor suppression." (PMID 38456941, 2024). "The interaction between CX3CL1 and CX3CR1 regulates the adhesion of immune cells to tumor cells, influencing the metastatic potential of cancer." (PMID 38456941, 2024). "They observed that the anti-VEGF drugs not only increased the content of CX3CL1 and CXCL5 in tumor vessels but also promoted the recruitment of neutrophils, resulting in the release of a large amount of the cytokine IL-10 to inhibit the adaptive immunity." (PMID 38534538, 2024). "More directly, in vivo studies have shown that co-expression of CX3CL1 and CX3CR1 led to a more malignant tumor phenotype with increased microglia/macrophage infiltration and microvessel density, and shorter overall survival." (PMID 38893093, 2024). "Inflammatory mediators such as CX3CL1 and IL-13 in the HCC tumor microenvironment can regulate the infiltration of MDSCs that contribute to the immunosuppressive function of cytokine-induced killer cells." (PMID 38397901, 2024). "CX3CL1/CX3CR1 has a tumor-suppressive activity by recruiting antitumoral immune cells such as NK and T cells into the tumor microenvironment to control tumor growth." (PMID 39290304, 2024). "YTHDF2 stabilizes the CX3CL1 transcript in an manner dependent on m6A, modulating the interaction between CD8 T cells and thereby promoting treatment-induced anti-tumor immune responses in the liver." (PMID 39593172, 2024). "To identify the relationship between increasing VLSs and CX3CL1, we analyzed the histopathological locations of increasing CX3CL1+ and CX3CR1+ structures in MOC2CX3CL1 tumor tissues." (PMID 38775151, 2024).